LRIG1 (leucine rich repeats and immunoglobulin like domains 1)
Diseases named in the same sentence as LRIG1 in open-access papers (continued):
Sharing a sentence is not in itself a finding about the gene and the disease.
bladder cancer (continued). "Moreover, we found a positive correlation between the expression levels of circLRIG1 and LRIG1 in bladder carcinoma tissues." (PMID 38454507, 2024). "Additionally, Western blot analysis revealed that LRIG1 overexpression increased the protein level of E-cadherin but decreased the protein level of N-cadherin and Vimentin in bladder carcinoma cells." (PMID 38454507, 2024). "To investigate whether circLRIG1 is involved in the progression of bladder carcinoma by regulating the miR-214-3p/LRIG1 axis, we first silenced LRIG1 in bladder carcinoma cell lines (UMUC3 and T24) by transfecting them with si-LRIG1." (PMID 38454507, 2024). "In our study, we confirmed that LRIG1 is diminished in bladder carcinoma tissues and cell lines." (PMID 38454507, 2024). "Furthermore, aberrant expression of LRIG1 has been identified as a significant factor in bladder carcinoma tumorigenesis and progression." (PMID 38454507, 2024). "Furthermore, we found that overexpression of circLRIG1 can impair cell growth, migration, invasion, and promote cell apoptosis in bladder carcinoma cells, but overexpression of miR-214-3p or LRIG1 silencing can reverse these effects." (PMID 38454507, 2024). "Notably, as core genes in the networks, AHCY, C6orf136 and LRIG1 show high potential to be prognosticators for bladder cancer." (PMID 32065779, 2020). "Interestingly, the alteration located in LRIG1 had already been described in two cancer patients, one with a colon adenocarcinoma and the other with bladder cancer." (PMID 32796636, 2020). "Taken together, we conclude that restoration of LRIG1 to bladder cancer could offer a novel therapeutic strategy for suppression of receptor-positive bladder cancer." (PMID 24314030, 2013). "LRIG1 cDNA exerted a profound effect on cell invasion in the two bladder cancer cells." (PMID 24314030, 2013). "Finally, we demonstrated the capacity of upregulation of LRIG1 to inhibit downstream EGFR signaling in bladder cancer cells as manifested by markedly decreased expression of p-MAPK and p-AKT." (PMID 24314030, 2013). "Taken together, these results could offer a novel therapeutic strategy for suppression of bladder cancer by restoration of LRIG1." (PMID 24314030, 2013). "IHC staining also demonstrated downregulation of LRIG1 protein in bladder cancer tissue." (PMID 24314030, 2013). "Furthermore, we evaluate the impact of LRIG1 gene on the function of human bladder cancer cells and EGFR signaling." (PMID 24314030, 2013). "This phenomenon could indicate that the expression of LRIG1 were lower in aggressive bladder cancer." (PMID 24314030, 2013). "We next transfected bladder carcinoma cell lines (UMUC3 and T24) with miR-214-3p mimics and found that the protein expression of LRIG1 was reduced." (PMID 38454507, 2024). "In order to examine the mRNA expression of LRIG1 and EGFR in bladder cancer, 45 tumor RNA samples and corresponding 5 normal tissues RNA samples were analyzed by quantitative real-time RT-PCR." (PMID 24314030, 2013). "In this study, we examined the mRNA and protein expression of LRIG1 and EGFR in bladder cancers and normal bladder." (PMID 24314030, 2013). "In this study, we observed that LRIG1 expression appeared significantly downregulated, but EGFR markly elevated in the majority of bladder cancer compared to human normal bladder tissue." (PMID 24314030, 2013). "Recently, leucine-rich repeats and immunoglobulin-like domains 1 (LRIG1), a negative regulator of EGFR, was discovered is a novel agent for suppressing bladder cancer." (PMID 24314030, 2013). "In order to detect the relationship between LRIG1 and EGFR on bladder cancer cells, we examined the expression level of EGFR on T24 and 5637 cells after transfection of LRIG1 cDNA." (PMID 24314030, 2013). "The expression of LRIG1 was decreased, while the expression of EGFR was increased in the majority of bladder cancer, and the ratio of EGFR/LRIG1 was increased in tumors versus normal tissue." (PMID 24314030, 2013).
bladder cancer (continued). "The results showed that LRIG1 expression was significantly lower in bladder carcinoma tissues compared to adjacent noncancerous specimens." (PMID 38454507, 2024). "We first detected the mRNA level of LRIG1 in bladder carcinoma tissues and adjacent noncancerous specimens using qRT-PCR assay." (PMID 38454507, 2024). "But the impact of LRIG1 on the biological behaviors of aggressive bladder cancer cells in vitro and the possible mechanisms of enhanced apoptosis induced by upregulation of LRIG1 is not very clear." (PMID 24314030, 2013). "Previous studies showed that upregulation of LRIG1 expression in the superficial bladder cancer BIU-87 cell lines resulted in inhibition of cell proliferation and attenuation of cell invasive abilities, and played a tumor-suppressive role in vivo in bladder cancer." (PMID 24314030, 2013). "To determine whether EGFR expression is critical for the effect of LRIG1 on bladder cancer cells in vitro, we next used specific genetic inhibition of EGFR to assess the consequences of its inhibition on LRIG1 mediated cell proliferation and signal pathway regulation." (PMID 24314030, 2013). "Taken together, our findings provide us with an insight into LRIG1 function, and we conclude that LRIG1 evolved in bladder cancer as a rare feedback negative attenuator of EGFR, thus could offer a novel therapeutic target to treat patients with bladder cancer." (PMID 24314030, 2013). "We also examined the protein expression of LRIG1 in three pairs of bladder carcinoma tissues and adjacent noncancerous specimens using Western blot analysis, and the data suggested that the protein expression of LRIG1 was decreased in bladder carcinoma tissues." (PMID 38454507, 2024).
colorectal cancer (6 papers, 2013 to 2024). A primary or metastatic malignant neoplasm that affects the colon or rectum. "This epigenetic regulation of LRIG1 was concordant with reports of colorectal cancer and cholangiocarcinoma." (PMID 34576152, 2021). "The tumor LRIG1-positive rate in colorectal cancer tumors was 37.4%, which was significantly lower than that in control tissues (57.7%, P < 0.05)." (PMID 33461538, 2021). "One hundred and two patients with colorectal cancer were retrospectively analyzed for LRIG1 expression at both mRNA and protein levels." (PMID 33461538, 2021). "Some genes, such as K-ras and epidermal growth factor receptor (EGFR) and human epidermal growth factor receptor 2 (HER2) are reported to be involved in the progress and development of colorectal cancer, but the LRIG1 roles in colorectal cancer have not been well studied and remained contradictory." (PMID 33461538, 2021). "Here the LRIG1 expression in the lesions of CRC patients was studied in order to evaluate its relationship with the major clinicohistological predictive factors and its respective impacts on patient prognosis hoping to improve the approaches for colorectal cancer management." (PMID 33461538, 2021). "Therefore, it is suggested that LRIG1 expression analyses may not be important when making informed and individualized clinical decisions regarding the management of colorectal cancer patients." (PMID 33461538, 2021). "Therefore, it is suggested that LRIG1 expression analyses may not be considered as an important issue when making informed and individualized clinical decisions regarding the management of colorectal cancer patients." (PMID 33461538, 2021).
cervical cancer (5 papers, 2017 to 2025). A primary or metastatic malignant neoplasm involving the cervix. "In cervical cancer, the variation in the number of LRIG1 gene copies and promoter methylation patterns are associated with patient survival." (PMID 28841699, 2017). "LRIG1 expression is of prognostic significance and is associated with good prognosis in various human cancers, including cervical cancer, non-small-cell lung cancer, breast cancer, and others." (PMID 28841699, 2017). "Hence, LRIG1 expression is associated with better survival in head and neck cancer, breast cancer, non‐small‐cell lung cancer, and cervical cancer." (PMID 40702701, 2025). "Leucine‐rich repeats and immunoglobulin‐like domains protein 1 (LRIG1) is a regulator of growth factor signaling and a prognostic factor in cervical cancer." (PMID 40702701, 2025). "Our findings support further investigation of LRIG1 as a biomarker to improve staging accuracy and guide treatment decisions in cervical cancer patients." (PMID 40702701, 2025). "Our results indicate that the use of LRIG1 expression as a potential biomarker for lymph node involvement in patients with cervical cancer should be further explored." (PMID 40702701, 2025). "For the first time, we demonstrated that high LRIG1 immunoreactivity predicts LNM in cervical cancer patients (adjusted OR 9.49, 95% CI: 1.80–50.05, P = 0.008)." (PMID 40702701, 2025). "Previous studies on LRIG1 expression in cervical cancer have focused on its potential for use as a prognostic marker." (PMID 40702701, 2025). "Previous studies on LRIG1 expression in cervical cancer reported that high LRIG1 expression was a positive prognostic factor in early‐stage squamous cell carcinoma and adenocarcinoma." (PMID 40702701, 2025). "Studying LRIG1 blood levels in cervical cancer patients could provide a less invasive alternative to biopsy‐based testing that should be further evaluated for use as a biomarker." (PMID 40702701, 2025). "Since LRIG1 expression was a prognostic factor in cervical cancer, we wanted to investigate whether LRIG1 expression might also predict LNM in cervical cancer patients." (PMID 40702701, 2025). "Immunohistochemical staining of a cervical cancer biopsy sample could be used preoperatively to assess LRIG1 expression and guide treatment decisions." (PMID 40702701, 2025). "In the cervical carcinomas analyzed here, LRIG1 immunoreactivity was mainly nuclear." (PMID 40702701, 2025). "Prior studies in colorectal and cervical cancers indicate that the LRIG1 locus is hypermethylated." (PMID 35440669, 2022). "Interestingly, hypermethylation of the LRIG1 promoter region has been reported in colorectal cancer as well as cervical cancer, where it was found to correlate with decreased progression-free survival." (PMID 35440669, 2022). "In general, high expression of LRIG1 and LRIG3 in tumours is associated with improved survival in cancer patients, whereas high expression of LRIG2 is associated with poor survival even in early-stage cervical cancer patients." (PMID 28841699, 2017). "This study investigates whether LRIG1 expression could predict LNM in cervical cancer." (PMID 40702701, 2025). "We investigated whether LRIG1 expression could predict LNM in patients with cervical cancer." (PMID 40702701, 2025). "Likewise, future retrospective and prospective studies in independent, larger cohorts will be necessary to assess whether LRIG1, either alone or in combination with other biomarkers, can reliably predict lymph node metastasis in early‐stage cervical carcinoma in a clinically meaningful way." (PMID 40702701, 2025). "The expression of the human leucine-rich repeats and immunoglobulin-like domains (LRIG) proteins LRIG1, LRIG2, and LRIG3 has emerged as a new potential prognostic biomarker in different types of human cancer, including cervical cancer." (PMID 28841699, 2017). "The upregulation of LRIG1+ cells is correlated to HPV+ oropharyngeal and cervical cancers as well." (PMID 36016373, 2022).
colon carcinoma (5 papers, 2019 to 2025). "HCT116 colon carcinoma cells were included as a positive control, as they are reported to have high levels of LRIG1 CpG island methylation." (PMID 35440669, 2022). "Consistent with these prior findings, Oct1 loss accelerated tumorigenesis and increased tumor number in a colon cancer model driven by LOH of the tumor suppressor gene Apc in Lrig1+ cells." (PMID 31059499, 2019). "In addition, in another public transcript data set (GSE76342) for the colon cancer cell line LoVo with or without metformin treatment, we found that metformin inhibited expression of the CSC markers Lgr5, ASCL2, EPHB3, OLFM4, BMI1, Lrig1, TERT, CD44, and CD133." (PMID 32911743, 2020).
ovarian carcinoma (5 papers, 2018 to 2025). A malignant neoplasm originating from the surface ovarian epithelium. "The authors speculate that this could be connected to the BMP-promoting effect of LRIG1, as BMPs are associated with tumor-stimulating functions in ovarian carcinoma." (PMID 38918827, 2024). "Rather, the expression of LRIG1 in the LRIG1-inducible MEFs was similar to the expression level in human ovarian carcinoma cells, showing that the expression system produced physiological LRIG1 levels." (PMID 37603563, 2023). "We found that the expression of BANF1, CDK2AP2, DDT, LRIG1, MRPL4, and S100A13 was upregulated in ovarian cancer samples, and the expression of EPS8, NUCB2, PAF1, PMP22, RABGAP1L, and USO1 was upregulated in normal samples." (PMID 41000388, 2025).
prostate carcinoma (5 papers, 2012 to 2024). A carcinoma that arises from epithelial cells of the prostate gland. "Surprisingly, despite the large body of knowledge on LRIG1 in many tissues and tumor systems, little is known, and few papers have been published, about LRIG1 functions and regulation in prostate cancer (PCa)." (PMID 31792211, 2019). "In an untreated prostate cancer cohort, LRIG1 was a marker for poor survival." (PMID 38918827, 2024). "However, little is known about the expression, regulation and biological functions of LRIG1 in prostate cancer (PCa)." (PMID 31792211, 2019). "However, LRIG1 expression has also been shown to be up-regulated in prostate cancer and leukemia which highlighted that LRIG1 might act as an oncogene depending on the cellular contexts." (PMID 22589739, 2012).
psoriasis (5 papers, 2013 to 2023). An autoimmune condition characterized by red, well-delineated plaques with silvery scales that are usually on the extensor surfaces and scalp. "Also, Lrig1 KO mice show psoriasis-like epidermal hyperplasia with the over-proliferative ability of keratinocytes, and further loss of Lrig1 causes chronic inflammation through the STAT3-dependent pathway." (PMID 37666819, 2023). "Several psoriasis-related genes were among the associated genes of hsa_skin_088763, including GATA6, SIK2, IL17RD, EGR3, FAS, LRIG1, and PPARGC1A." (PMID 34068434, 2021). "In support of this, Lrig1 regulates EGFR levels in primary human keratinocytes, and loss of Lrig1 results in increased EGF signaling and excess intestinal stem cell proliferation, tumor formation and psoriasis-like hyperplasia in mice." (PMID 24086156, 2013). "LRIG1 negatively regulates growth factor signaling to regulate epidermal stem cell quiescence; SIK2 modulates cytokine responses during innate immune activation; FAS signaling is essential for inducing key inflammatory cytokines in psoriasis." (PMID 34068434, 2021). "As negative control for Lrig1 staining, we stained psoriatic epidermis and confirmed the total lack of Lrig1 signal, while expression of keratin 5 was normally detected in keratinocytes of the basal layer in SAHE, HHE and psoriasis." (PMID 28099467, 2017).
squamous cell carcinoma (5 papers, 2007 to 2025). A carcinoma arising from squamous epithelial cells. "The expression of LRIG1 mRNA was significantly higher in adenocarcinoma (AC) compared with that in squamous cell carcinoma (SCC) (P = 0.004)." (PMID 26632716, 2015). "In agreement with our results, previous studies on squamous cell carcinomas of the cervix and oropharynx, breast, skin, and non-small cell lung cancer showed that high LRIG1 expression is associated with improved prognosis." (PMID 28841699, 2017). "Moreover, in squamous cell carcinoma, low levels of LRIG1 expression has been correlated with increased metastasis and poor patient survival, suggesting that the down-regulation of LRIG1 provides a novel prognostic predictor in this malignancy." (PMID 19662191, 2007).
adenoma (4 papers, 2018 to 2021). A neoplasm arising from the epithelium. "Adenomas resulting from the inducible loss of one copy of Apc in Lrig1+/−-expressing colonic stem cells are hypermutated and genetically heterogeneous." (PMID 32059662, 2020). "The loss of a single copy of adenomatous polyposis coli (Apc) in leucine-rich repeats and immunoglobulin-like domains 1 (Lrig1)-expressing colonic progenitor cells induces rapid growth of adenomas in mice with high penetrance and multiplicity." (PMID 32059662, 2020). "The high incidence of Lrig1-CreERT2/+;Apcfl/+ adenomas localized to the distal colon might be explained by the high levels of ROS inherent to the distal colon and rectum." (PMID 32059662, 2020).
breast tumors (4 papers, 2005 to 2022). "Analysis of mRNA read count (RNASeqV2) confirmed that LRIG1 is most significantly reduced in basal breast tumours." (PMID 35440669, 2022). "We demonstrate that LRIG1 methylation is significantly increased in breast tumours compared to normal tissue, with a strong inverse correlation between LRIG1 mRNA expression and CpG island methylation." (PMID 35440669, 2022). "Patients whose breast tumours expressed higher levels of LRIG1 methylation had decreased overall survival time, suggesting that LRIG1 promoter methylation is functionally important." (PMID 35440669, 2022). "Analysis of methylation status using the HumanMethylation450 array revealed that methylation (β-value) at the LRIG1 CpG island is significantly increased in breast tumours (n = 796) compared to normal samples (n = 96)." (PMID 35440669, 2022). "In the present study, 12.5% of the tumors displayed LRIG1 gains, contrasting with our previous FISH results showing that 39% of breast tumors displayed LRIG1 gains." (PMID 32448168, 2020). "Based on this finding, we concluded that 2.9% (1/34) of the breast tumors in this series had undergone an unbalanced LRIG1 gene recombination event." (PMID 32448168, 2020). "In our previous studies, in which fluorescence in situ hybridization (FISH) was used to determine gene copy numbers, LRIG1 showed increased and decreased copy numbers in 34 and 3.5% of breast tumors, respectively." (PMID 32448168, 2020). "In one of the breast tumours with increased copy number of LRIG1 (patient B8), a more detailed FISH analysis was performed to assess the chromosome 3 status and the ploidity of the tumour cells." (PMID 16168117, 2005). "Kaplan–Meier analysis of ER-negative patients revealed that patients whose breast tumours expressed higher levels of LRIG1 methylation, at these enhancer-region CpG sites, had decreased overall survival time, suggesting that methylation at both elements is functional." (PMID 35440669, 2022). "We developed droplet digital PCR (ddPCR) assays for the determination of relative LRIG1 copy numbers and used these assays to analyze LRIG1 in twelve healthy individuals, 34 breast tumor samples previously analyzed by fluorescence in situ hybridization (FISH), and 423 breast tumor cytosols." (PMID 32448168, 2020). "In total, 28 breast tumours were analysed by FISH with LRIG1 specific probe." (PMID 16168117, 2005).
cervical adenocarcinoma (4 papers, 2015 to 2024). An adenocarcinoma arising from the cervical epithelium. "Interestingly, LRIG1 expression has been found to be associated with favorable prognosis and presence of human papillomavirus DNA in both oropharyngeal cancer and cervical adenocarcinoma." (PMID 34331569, 2021). "Furthermore, increasing LRIG1 expression has been correlated with increasing grade of cervical intraepithelial neoplasia and has also been observed as a prognostic marker in cervical adenocarcinoma." (PMID 28841699, 2017). "In oropharyngeal cancer, with a sample size of 278 patients, LRIG1 expression was also reported to be an independent prognostic marker in Cox regression multivariate analysis, whereas in cervical adenocarcinoma (sample size 86 patients), it was not." (PMID 34331569, 2021).